OR7G1 (olfactory receptor family 7 subfamily G member 1)
Description:
Odorant receptor.
Synonyms: OR19-15; OR7G1P; OR19-8
Tractability: Antibody: UniProt places it where antibodies can reach, with medium confidence; UniProt predicts a signal peptide or a membrane-spanning region; its Gene Ontology location is reachable by antibodies, with medium confidence.
Gene: Protein-coding gene on chromosome 19 (9,114,828 to 9,115,763, reverse strand). Ensembl gene ENSG00000161807.
Subcellular location: Cell membrane
Pathways (Reactome):
Sensory Perception: Expression and translocation of olfactory receptors
Gene Ontology:
Molecular function: olfactory receptor activity; G protein-coupled receptor activity; signaling receptor activity
Biological process: signal transduction; detection of chemical stimulus involved in sensory perception of smell; G protein-coupled receptor signaling pathway; sensory perception of chemical stimulus
Cellular component: plasma membrane; membrane
Genetic constraint (gnomAD): Missense variants: 385 observed, 384.64 expected, observed/expected ratio (o/e) 1, 90% interval 0.92 to 1.09. Synonymous variants: 142 observed, 146.86 expected, observed/expected ratio (o/e) 0.97, 90% interval 0.84 to 1.11.
Homologues: Orthologues: chimpanzee OR7G1 (97% identical), dog OR7G8 (78% identical), dog OR7G14 (78% identical), dog OR7G5 (77% identical), dog OR7G9 (77% identical), rat Or7g17 (65% identical), rat Or7g31 (65% identical), rat Or7g34 (65% identical), mouse Or7g34 (65% identical), rat Or7g34b (65% identical), mouse Or7g17 (65% identical), mouse Or7g25 (65% identical), and 6 more. Paralogues in human: OR7G2 (74% identical), OR7G3 (66% identical), OR7A10 (60% identical), OR7C2 (60% identical), OR7A5 (60% identical), OR7C1 (60% identical), OR7A17 (59% identical), OR7D4 (59% identical), OR7E24 (57% identical), OR7D2 (55% identical), OR1I1 (50% identical), OR1G1 (49% identical), and 116 more.